CX3CL1 (C-X3-C motif chemokine ligand 1)
Diseases named in the same sentence as CX3CL1 in open-access papers (continued):
Sharing a sentence is not in itself a finding about the gene and the disease.
breast carcinoma (continued). "Additionally, the recruitment of monocytes through CX3CL1 occurs in in vivo models of such cancers as human breast cancer line HS578T, human colorectal adenocarcinoma line DLD1 and human colorectal carcinoma line HCT116." (PMID 32466280, 2020). "New research found that in most types of breast cancer patients, high levels of CCL5 in plasma promote the expression of CX3CL1 to promote breast cancer cell proliferation through epidermal growth factor signal transduction pathway, and also promote epithelial‐mesenchymal transition." (PMID 32253815, 2020). "Moreover, chemokine CX3CL1 has been demonstrated to mediate specific metastasis of breast cancer to the bone marrow." (PMID 33123472, 2020). "The level of CX3CL1 in the serum samples from the metastatic spinal tumors was 0.63 ± 0.05 ng/ml in lung cancer, 0.61 ± 0.08 ng/ml in liver cancer, 0.58 ± 0.06 ng/ml in breast cancer, 0.69 ± 0.13 ng/ml in kidney cancer, and 0.71 ± 0.12 ng/ml in prostate cancer." (PMID 28122354, 2017). "Fractalkine, another chemokine, CX3CL1, has also been implicated in the recruitment of macrophages since the administration of anti-CX3CR1 antibody decreased macrophage infiltration and angiogenesis in breast cancer." (PMID 28197019, 2017). "It was recently reported by Tsang that CX3CL1 could have a pro-tumor role in breast cancer, because breast cancers with a high expression of CX3CL1 were found to have poorer overall survival." (PMID 28122354, 2017). "Interestingly, CCL9 and CX3CL1 were strongly and uniformly elevated in the liver-metastatic breast cancer cells." (PMID 25882816, 2015). "In addition, relationships between CX3CL1 expression and patient prognosis are demonstrated in breast cancer." (PMID 24799766, 2014). "In addition to studying CX3CL1, previous studies have examined expression of CX3CR1 on breast cancer cells and the autocrine effects of the CX3CL1/CX3CR1 axis on regulating breast cancer cell migration." (PMID 23029290, 2012). "However, the link between FGFR activity, CX3CL1 expression and macrophage infiltration, and how these correlate with breast cancer subtype and patient outcome remain to be further determined." (PMID 23029290, 2012). "Thus, overexpression of genes including CX3CL1, FURIN and MTLG was associated with poor prognosis in breast cancer patients but a favourable outcome in prostate cancer patients." (PMID 17183660, 2006). "However, in breast cancer and HCC, increased CX3CL1 expression has been linked to poor outcomes." (PMID 40051011, 2025). "Therefore, CX3CL1 expression could be considered an essential biomarker for predicting prognosis and identify patients eligible for immunomodulating therapy in breast cancer." (PMID 24799766, 2014). "Moreover, recent studies indicate a role for CX3CR1/CX3CL1 in mediating cross-talk between tumor cells and their surrounding microenvironment in models of lymphocytic leukemia, glioblastoma, neuroblastoma, pancreatic cancer, prostate cancer, and breast cancer." (PMID 23029290, 2012). "CX3CL1 overexpression recruited NK cells and increased NK cell-mediated cytotoxicity in HER-2 positive breast cancer." (PMID 36601109, 2022). "There were seven shared hub nodes (FPR2, CXCR4, FPR1, CX3CL1, GPR37, GABBR2 and PLCB1) between metastatic breast cancer cell lines." (PMID 35045088, 2022). "Protein-protein interaction (PPI) analysis revealed seven shared (PLCB1, FPR1, FPR2, CX3CL1, GABBR2, GPR37, and CXCR4) hub genes between brain and lung metastasis in breast cancer." (PMID 35045088, 2022). "It has been reported that the increased expression of CX3CL1 correlates with the infiltration of CD8+ T cells and NK cells and better clinical outcomes in colon cancer, breast cancer, and lung cancer." (PMID 34885241, 2021). "Here, we investigated the impact of CX3CL1 overexpression in MDA-MB-453 and SK-BR-3 breast cancer cells." (PMID 34070094, 2021). "CX3CL1 and CXCL13 were found to be elevated in the sera of patients with breast cancer brain metastases." (PMID 33466236, 2021).
breast carcinoma (continued). "High levels of CX3CL1 in cells can attract those cancer cells expressing its receptor CX3CR1 and trigger them to invade the tissue and form metastases as seen e.g. in breast cancer spinal metastases." (PMID 32321535, 2020). "Among the chemokines tested, CX3CL1 and CXCL13 were selectively and significantly increased in patients with cerebral metastases of breast cancer." (PMID 32321535, 2020). "Metastatic breast cancer cells expressed chemokines that can direct the recruitment of T lymphocytes (CXCL9, CCL2 or CX3CL1)." (PMID 25882816, 2015). "Previous analysis of serum from patients with breast cancer and cerebral metastases found increased levels of CX3CL1 and CXCL13 (levels of CCL2 among other chemokines were not elevated)." (PMID 37924145, 2023). "Experimentally, it was shown that CX3CL1 can promote EMT in breast cancer cells, but this was not promoting metastatic spread to lymph nodes when cells were injected into mice." (PMID 38055067, 2023). "CX3CL1 and CXCL13 were shown to play an important role in the brain extravasation of breast cancer, while the following cytokines/chemokines were involved in the extravasation of melanoma cells (9IL-23, CXCL10, CXCR3, CXCL10 receptor, CCR4, CCL17, and CCR4) and lung cancer cells (TNF-α and CX3CR1)." (PMID 37190188, 2023). "Sera with elevated CX3CL1 and CXCL13 levels displayed barrier-compromising effects in vitro and therefore could contribute to the formation of brain metastases by breast cancer cells in vivo." (PMID 32321535, 2020). "The CX3CR1/CX3CL1 and CXCR3/CXCL10 axes have been demonstrated to be involved in the proliferation, survival, and metastasis of various malignant tumor types, including breast cancer, and were suggested to predict the site of metastatic relapse." (PMID 31026363, 2019). "The expression of CX3CL1 and CXCL16 was confirmed on protein level by immunocytochemistry, which revealed high expression for the brain tumor cell lines and low expression for the breast carcinoma cell line MCF-7." (PMID 26796342, 2016). "In vitro studies revealed that the chemokine (C-X-C motif) ligand CX3CL1 and CXCL13 levels were elevated in the serum of breast cancer patients with brain metastases, indicating that the presence of these chemokines may disrupt the integrity of the BBB and thus are implicated in the process of BM." (PMID 37190188, 2023). "Indeed, high expression of the CX3CL1 molecule by tumor cells was found to correlate with a good prognosis and with increased tumor-infiltrating CD8+ T cells, natural killer cells, and dendritic cells in breast carcinoma." (PMID 30108590, 2018). "The screening results showed that none of the receptors for Cx3cl1 (CX3CR1), Cxcl16 (CXCR6), Ccl17 (CCR4, DARC, CCR10) or IL6 (IL6R) was more expressed in basal B compared to basal A or luminal breast cancer cells." (PMID 38055067, 2023). "Breast cancer cells that express high levels of CX3CR1 have a greater propensity toward bone metastasis; consistent with these data, studies in CX3CL1-null transgenic mice suggest that the absence of this chemokine impairs the dissemination of cancer cells to bone." (PMID 25165728, 2014).
Alzheimer disease (47 papers, 2011 to 2026). A progressive, neurodegenerative disease characterized by loss of function and death of nerve cells in several areas of the brain leading to loss of cognitive function such as memory and language. "Activated Cx3cl1 signalling shows neuroprotective effects and prevents neuronal loss in Alzheimer’s disease." (PMID 35850611, 2022). "Enhancing neuronal CX3CL1, mainly the C-terminal fragment, is a therapeutic strategy for blocking or reversing neuronal loss in Alzheimer's disease or related neurodegenerative disease patients." (PMID 31822518, 2020). "Urinary CX3CL1 levels correlate with the aging process and may serve as a potential diagnostic biomarker for both amnestic mild cognitive impairment (aMCI) and Alzheimer’s disease (AD)." (PMID 39917031, 2025). "CX3CL1 ICD may hold significant translational potential for neuroprotection in Alzheimer’s disease and for disorders associated with insulin resistance." (PMID 40927393, 2025). "The biomarker CX3CL1, which is also commonly known as Fractalkine in humans, was independently associated with all-cause dementia and among the list of statistically significant biomarkers for Alzheimer’s disease and vascular dementia in our study." (PMID 36085081, 2022). "The observed neurogenesis in Tg-CX3CL1 mice prompted us to test whether enhanced adult neurogenesis would be beneficial for reversing neuronal loss in neurodegenerative diseases such as Alzheimer's disease." (PMID 31822518, 2020). "Cx3cr1, the receptor for the chemokine Cx3cl1 (fractalkine), has been implicated in the progression and severity of Alzheimer’s disease-like pathology in mice, but the underlying mechanisms remain unclear." (PMID 26038823, 2015). "For this purpose, they quantified the concentration of CX3CL1 in plasma from healthy subjects and patients with mild cognitive impairment or different degrees of Alzheimer’s disease." (PMID 39940727, 2025). "Despite the disparity regarding the main conclusion of both articles, it is worth noting that, in all cases, the accumulation of CX3CL1 was lower in the most advanced Alzheimer’s disease cases analyzed." (PMID 39940727, 2025). "Based on the results provided by these studies, it can be concluded that CX3CL1 plays a significant role in the progression of Alzheimer’s disease." (PMID 39940727, 2025). "Later analyses of expression confirmed the elevation of CX3CL1 levels in the hippocampus of Alzheimer’s disease patients." (PMID 39940727, 2025). "For this reason, similarly to Alzheimer’s disease, the analysis of the CX3CL1/CX3CR1signaling system in Parkinson’s disease constitutes a relevant area of study." (PMID 39940727, 2025). "The role of the chemokine CX3CL1 in the processes of aging and Alzheimer’s disease (AD) pathogenesis is well-established." (PMID 39917031, 2025). "For this reason, different strategies have been used to increase or reduce the synthesis of CX3CL1 and explore if it has an effect on Alzheimer’s disease models." (PMID 39940727, 2025). "More interestingly, in agreement with the variations found in plasma levels, also on this occasion, CX3CL1 was found to be more abundant in the samples obtained from intermediate Alzheimer’s disease cases, while it was reduced in the advanced ones." (PMID 39940727, 2025). "This study aimed to investigate the impact of repetitive transcranial magnetic stimulation (rTMS) on cognitive recovery in Alzheimer's disease (AD) by exploring the role of GABAergic neuron activation and modulation of the Cx3cl1‐Cx3cr1 signalling axis." (PMID 40415257, 2025). "In contrast, this finding also showed reduced CX3CL1 levels in the Alzheimer’s disease autopsy brain sections." (PMID 36831001, 2023). "In this review, the dual roles of CX3CL1 and ADAMs/MMPs in different neurodegenerative diseases, such as Alzheimer’s disease (AD), Parkinson’s disease (PD), Huntington’s disease (MH), and multiple sclerosis (MS), are investigated." (PMID 37175729, 2023).
Alzheimer disease (continued). "In Alzheimer’s disease, CX3CL1 expression is reduced in the main areas where the pathological changes occur and its expression levels reflect the progression of the disease." (PMID 35783096, 2022). "Regarding other neuropsychiatric disorders, the CX3CL1/CX3CR1 axis was shown to contribute to the pathology of Alzheimer's disease (AD) by altering the levels of Tau protein and the process of Tau phagocytosis in microglia cells." (PMID 35782435, 2022). "CX3CL1 is also decreased in the cerebrospinal fluid of patients with Alzheimer’s disease, and patients with mild to moderate Alzheimer’s disease have significantly higher plasma CX3CL1 levels compared to patients with the severe form of the disease." (PMID 35783096, 2022). "Microglial CX3CR1/CX3CL1 axis plays a significant role in the progression of Alzheimer’s disease with controversy in Aβ and Tau pathology." (PMID 32944223, 2020). "The therapeutic potential of CX3CL1 in Alzheimer’s disease is more complex; however, knockout of CX3CR1 appears to be detrimental in mouse models of tauopathy, but beneficial in amyloid expressing mice." (PMID 32410624, 2020). "Levels of CX3CL1 have been shown to be reduced in aged animals and CSF from Alzheimer’s disease patients." (PMID 32410624, 2020). "In Alzheimer’s disease (AD), CX3CL1/CX3CR1 blockade modulates microglia phagocytic activity in a way that markedly attenuates amyloid deposition." (PMID 25152714, 2014). "Given the signaling nature of CX3CL1 and its altered levels in Alzheimer’s disease, this chemokine has been considered as a potential tool that may alter the progression of the pathology." (PMID 39940727, 2025). "However, contradictory results have been described when the concentration of CX3CL1 was measured in cerebrospinal fluid samples obtained from patients suffering from mild cognitive impairment or Alzheimer’s disease." (PMID 39940727, 2025). "Considering these reports, and the apparent correlation between brain and blood levels, it has been proposed that plasma concentrations of CX3CL1 could be used as an additional marker to diagnose Alzheimer’s disease." (PMID 39940727, 2025). "It is well known that in the pathology of Alzheimer’s disease, there is a condition of generalized and progressive inflammation during its evolution, both occurring in the brain system, then endothelial cells expressing CX3CL1 and its receptor CX3CR1." (PMID 38473758, 2024). "Previous reports indicated that CX3CL1 exerts a neuroprotective effect by targeting activated microglia, which has been demonstrated in rodent models of stroke, Parkinson’s disease, and Alzheimer’s disease." (PMID 37605279, 2023). "CX3CL1 has been shown to signal through P38 MAPK in an Alzheimer’s disease study." (PMID 36835011, 2023). "Taken together, our results suggest that CX3CL1-ICD may have translational potential for neuroprotection in Alzheimer’s disease and for disorders resulting from insulin resistance." (PMID 36162508, 2022). "Moreover, additional studies have reported that mild–moderate Alzheimer’s disease patients had higher plasma levels of CX3CL1 than those with severe Alzheimer’s disease." (PMID 35625687, 2022). "The identified independent biomarkers include CX3CL1 (associated with all-cause dementia), EN-RAGE (associated with all-cause dementia and Alzheimer’s disease), LAP TGF-beta-1 (associated with Alzheimer’s disease), and VEGF-A (associated with vascular dementia)." (PMID 36085081, 2022). "The role of CX3CL1 in Alzheimer's disease (AD) pathogenesis remains to be understood." (PMID 31822518, 2020). "However, in models of transient cerebral ischemia and Alzheimer's disease (AD), CX3CL1 is reported to play opposite roles." (PMID 25525298, 2014).
Alzheimer disease (continued). "Furthermore, when peripheral blood mononuclear cells (PBMCs) obtained from human donors were incubated with a blood–brain barrier in vitro model, those cells obtained from Alzheimer’s disease patients stimulated the production of CX3CL1 in both sides of the barrier." (PMID 39940727, 2025). "Therefore, CX3CL1 could represent a fundamental element for the slowdown of Alzheimer’s disease and a potential target for therapeutic intervention." (PMID 37175729, 2023). "Previous studies pointed out that astrocytes could also express CX3CL1 at lower levels than neurons, particularly in response to pro-inflammatory signals, which occurred in disorders such as stroke, multiple sclerosis, and Alzheimer's disease." (PMID 35990892, 2022). "The forward selection revealed that only two (CX3CL1 and EN-RAGE), two (EN-RAGE and LAP TGF-beta-1), and one (VEGF-A) inflammation-related proteins were independently, positively associated with all-cause dementia, Alzheimer’s disease, and vascular dementia, respectively." (PMID 36085081, 2022). "A recent Polish study reported on the predictive ability of CX3CL1 as a biomarker in the early development of mild cognitive impairment (MCI) and Alzheimer’s disease." (PMID 36085081, 2022). "In this study, significantly higher CSF and blood levels of CX3CL1 were found in MCI and Alzheimer’s disease patients compared to cognitively healthy controls." (PMID 36085081, 2022). "Contrariwise, the CX3CL1 membrane form in Alzheimer’s disease has a negative effect on preventing tau phagocytosis by its competition in binding the microglia receptor CX3CR1." (PMID 37175729, 2023). "For example, neuronal ligand CX3CL1 (fractalkine) signals to microglia through CX3CR1 altering immune signaling, synaptic plasticity, as well as amyloid β-complement processing in Alzheimer’s disease models." (PMID 30610351, 2019).